LEMD3 (LEM domain containing 3)
Description:
Can function as a specific repressor of TGF-beta, activin, and BMP signaling through its interaction with the R-SMAD proteins. Antagonizes TGF-beta-induced cell proliferation arrest.
Synonyms: MAN1
Tractability: Antibody: UniProt predicts a signal peptide or a membrane-spanning region. PROTAC: ubiquitination databases record sites on it; its protein half-life has been measured.
Gene: Protein-coding gene on chromosome 12 (65,169,342 to 65,248,355, forward strand). Ensembl gene ENSG00000174106.
Subcellular location: Nucleus inner membrane
Subcellular location (Human Protein Atlas): Nuclear membrane
Pathways (Reactome):
Signal Transduction: RAC1 GTPase cycle; RAC2 GTPase cycle; RAC3 GTPase cycle; RHOD GTPase cycle; RHOG GTPase cycle; RND1 GTPase cycle; RND2 GTPase cycle; RND3 GTPase cycle
Cell Cycle: Depolymerization of the Nuclear Lamina; Initiation of Nuclear Envelope (NE) Reformation; Nuclear Envelope Breakdown
Gene Ontology:
Molecular function: protein binding; U1 snRNP binding; nucleic acid binding
Biological process: negative regulation of activin receptor signaling pathway; negative regulation of BMP signaling pathway; negative regulation of transforming growth factor beta receptor signaling pathway
Cellular component: membrane; nuclear inner membrane; nuclear membrane; nuclear envelope
Genetic constraint (gnomAD): Loss-of-function variants: 20 observed, 49.74 expected, observed/expected ratio (o/e) 0.4, 90% interval 0.28 to 0.58. The synonymous counts are far from expectation, so gnomAD's model fits this gene poorly and the ratio says little. Missense variants: 997 observed, 894.63 expected, observed/expected ratio (o/e) 1.11, 90% interval 1.06 to 1.17. Synonymous variants: 455 observed, 374.48 expected, observed/expected ratio (o/e) 1.22, 90% interval 1.12 to 1.31.
Homologues: Orthologues: chimpanzee LEMD3 (99% identical), macaque LEMD3 (98% identical), pig LEMD3 (92% identical), rabbit LEMD3 (92% identical), rat Lemd3 (84% identical), mouse Lemd3 (83% identical), dog LEMD3 (83% identical), guinea pig LEMD3 (76% identical), tropical clawed frog lemd3 (50% identical), zebrafish lemd3 (42% identical), Drosophila melanogaster MAN1 (19% identical), Caenorhabditis elegans lem-2 (13% identical). Paralogues in human: LEMD2 (17% identical), ANKLE1 (12% identical).
Diseases named in the same sentence as LEMD3 in open-access papers:
LEMD3 is named in the same sentence as 21 diseases in open-access papers, as found by Europe PMC text mining. Sharing a sentence is not in itself a finding about the gene and the disease. The quoted sentences say what the papers report.
osteopoikilosis (16 papers, 2010 to 2025). A rare autosomal dominant inherited disorder characterized by the presence of small areas of increased density throughout the bones. "Melorheostosis concurrent with osteopoikilosis has been shown to be associated with the LEMD3 mutation." (PMID 39945784, 2025). "A loss-of-function mutation in the LEMD3 gene has been described in osteopoikilosis and Buschke-Ollendorff syndrome." (PMID 39945784, 2025). "In this regard, LEMD3 (MIM *607,844) is known as a causative gene for osteopoikilosis, because pathogenic loss-of-function variants in LEMD3 have been demonstrated in several families with autosomal-dominant osteopoikilosis." (PMID 38840187, 2024). "Osteopoikilosis is a rare autosomal dominant bone dysplasia caused by a loss-of-function mutation in the LEM domain containing 3 (LEMD3) gene which encodes for an inner nuclear membrane protein." (PMID 36292765, 2022). "A previous study has reported that loss-of-function mutations in LEMD3 contributed to osteopoikilosis, Buschke-Ollendorff syndrome, and melorheostosis." (PMID 32003753, 2020). "In this respect, it is noteworthy that mutations in MAN1 (also known as LEMD3) gene cause osteopoikilosis, a disease characterized by increased bone density." (PMID 29854317, 2018). "We report a unique familial LEMD3 mutation in an individual with osteopoikilosis and late-onset morphea." (PMID 27382493, 2016). "Here we describe a family with 5 patients affected by osteopoikilosis caused by novel mutation in the LEMD3 gene." (PMID 20618940, 2010). "Here we describe a familial case of osteopoikilosis in which a novel heterozygous LEMD3 mutation coincides with a novel mutation in EXT1, a gene involved in aetiology of multiple exostosis syndrome." (PMID 20618940, 2010). "We identified a family with five members affected by osteopoikilosis caused by a novel nonsense heterozygous mutation (p.R735X) localised in exon 9 of the LEMD3 gene." (PMID 20618940, 2010). "Surprisingly, three of the osteopoikilosis affected patients additionally to LEMD3 mutation carried a yet unreported amino acid variant (p.A578T) in the EXT1 gene." (PMID 20618940, 2010). "Osteopoikilosis is a rare and primarily benign autosomal dominant genetic entity caused by heterozygous mutations in the LEMD3 gene." (PMID 20618940, 2010). "In addition, different LEMD3 mutations have also been linked with nonsyndromic familial forms of both osteopoikilosis and melorheostosis." (PMID 27382493, 2016). "Presented study constitutes first example of the LEMD3 gene mutation co-occurrence with additional genetic alteration, which could potentially modify and/or constitute the nature of the osteopoikilosis." (PMID 20618940, 2010). "We identified a new mutation in LEMD3 gene, accounting for the familial case of osteopoikilosis." (PMID 20618940, 2010). "Mutations in MAP2K1 and SMAD3 have been identified in classical and endosteal forms of the disease, while LEMD3 alterations have been reported in osteopoikilosis‐related cases." (PMID 41214899, 2025). "After revealing a microdeletion involving HGMA2 and LEMD3, bone survey was performed at seven years of age, showing osteopoikilosis characterized by circular osteosclerotic dysplasia." (PMID 38840187, 2024). "In another study in humans, the role of LEMD3 in the pathogenesis of osteopoikilosis and short stature was highlighted." (PMID 36980905, 2023). "A favored alternative explanation is that late-onset generalized morphea associated with osteopoikilosis seen in the present case is in fact syndromic and represents a novel BOS variant that falls within the phenotypic continuum linked with LEMD3 mutations." (PMID 27382493, 2016). "We propose that in this case morphea and osteopoikilosis are linked, representing a novel BOS variant that is on the continuum of LEMD3-associated skin and bone manifestations." (PMID 27382493, 2016).
osteopoikilosis (continued). "Osteopoikilosis is caused by heterozygous loss of function mutations in the LEM domain-containing protein 3 46 (LEMD3) gene, also known as MAN1." (PMID 27267960, 2016). "The patients affected with both LEMD3 and EXT1 gene mutations displayed typical features of the osteopoikilosis." (PMID 20618940, 2010). "The data encourage re-evaluation of the known osteopoikilosis families for the possible co-occurrence of other than Buschke-Ollendorff and melorheostosis disease entities and investigation of the possible LEMD3 function in the DNA repair." (PMID 20618940, 2010). "Indeed, osteopoikilosis in group 2 has been identified only in patients missing LEMD3, with a reduced penetrance." (PMID 38840187, 2024). "In summary, we describe a case of osteopoikilosis associated with late-onset generalized morphea and associated LSA changes in an elderly individual carrying a previously undescribed familial mutation in LEMD3." (PMID 27382493, 2016). "We investigated LEMD3 and EXT1 in the three-generation family from Poland, with 5 patients affected with osteopoikilosis and one child affected with multiple exostoses." (PMID 20618940, 2010). "Loss of function of LEMD3 results in unique sclerosing bone disease spectrums, osteopoikilosis (MIM #166700), melorheostosis (MIM #155950) and Buschke-Ollendorff syndrome (BOS; MIM #166700).306,307 LEMD3 has been shown to antagonize BMP and TGF-β by interacting with SMAD-1, -2, -5, and -9." (PMID 38267638, 2024).
melorheostosis (15 papers, 2010 to 2025). Melorheostosis is a rare connective tissue disorder characterized by a sclerosing bone dysplasia, usually limited to one side of the body (rarely bilateral), that manifests with pain, stiffness, joint contractures and deformities. "Mutations in the LEMD3 gene have been identified in familial melorheostosis cases, indirectly linked to other dysplasias like osteopoikilosis." (PMID 38978887, 2024). "LEM domain-containing protein 3 (LEMD3) gene mutations have been correlated with several familial cases of melorheostosis." (PMID 36292765, 2022). "A survey of cases of LEMD3-associated skin and bony lesions revealed 28 cases of melorheostosis associated with linear scleroderma, typically affecting skin adjacent to the bone lesions, with a majority of these individuals developing linear (localized) scleroderma in childhood." (PMID 27382493, 2016). "Various pathogenic factors, including developmental, ischemic, telangiectatic, hypervascularity, and infection, are associated with melorheostosis, often co-occurring with OPK or LEMD3 mutations." (PMID 38978887, 2024). "In order to review current knowledge of BOS and its cutaneous manifestations, a PubMed survey using the search terms “BOS”, “Ollendorf Buschke”, “Buschke-Ollendorf”, “osteopoikilosis”, “melorheostosis”, “LEMD3”, and “Man1” was undertaken." (PMID 27382493, 2016). "As melorheostosis often coexists with OPK or within a family with LEMD3 mutations, the TGF-β/SMAD pathway may also contribute to melorheostosis pathogenesis." (PMID 37241101, 2023). "It has been speculated whether loss-of-function mutations in LEMD3 could be central to the pathophysiology of melorheostosis; this mutation is usually not present in cases of sporadic melorheostosis." (PMID 30257703, 2018). "However, melorheostosis frequently occurs in the absence of LEMD3 mutations, and thus far none of the LEMD3 mutation-proven cases of melorheostosis have coincided with linear scleroderma." (PMID 27382493, 2016). "In contrast, no germline LEMD3 mutations were found in the isolated cases of melorheostosis." (PMID 20618940, 2010). "Therefore, modern literature does not consider LEMD3 mutations to be the cause of melorheostosis." (PMID 36292765, 2022). "In fact, the majority of patients with melorheostosis display no LEMD3 abnormalities." (PMID 36292765, 2022).
Buschke-Ollendorff syndrome (6 papers, 2018 to 2025). Buschke-Ollendorff syndrome (BOS) is a benign disorder characterized by the association of osteopoikilosis lesions (``spotted bones'') in the skeleton and connective tissue nevi in the skin. "Buschke-Ollendorff syndrome, a rare disorder of increased bone density is caused by a loss-of-function mutation in the inner nuclear membrane protein, Man1 (also known as LEMD3)." (PMID 35784481, 2022).
Emery-Dreifuss muscular dystrophy (2 papers, 2012 to 2015). Emery-Dreifuss muscular dystrophy (EDMD) is characterized by muscular weakness and atrophy, with early joint contractures and cardiomyopathy. "For example, mutations in the gene for emerin (EMD) cause Emery-Dreifuss muscular dystrophy (EDMD), and mutations in the LEMD3 gene encoding MAN1 cause sclerosing bone dysplasias." (PMID 25790465, 2015).
liver fibrosis (2 papers, 2020 to 2023). "Our current study demonstrates that hsa_circ_0070963 plays a role in the progression of liver fibrosis by acting as a miRNA sponge for miR-223-3p and thereby promoting the function of LEMD3." (PMID 32003753, 2020). "Collectively, hsa_circ_0070963 appeared to function as a miR-223-3p sponge that inhibited HSC activation in liver fibrosis via regulation of miR-223-3p and LEMD3." (PMID 32003753, 2020). "In the present study, we demonstrated that a circRNA, named hsa_circ_0070963, may inhibit liver fibrosis by sponging miR-223-3p and targeting LEMD3." (PMID 32003753, 2020). "Next, we further sought to determine whether LEMD3 was involved in the effects of the hsa_circ_0070963-miR-223-3p axis on liver fibrosis." (PMID 32003753, 2020). "Our results illuminate a novel hsa_circ_0070963/miR-223-3p/LEMD3 signaling cascade in liver fibrosis, suggesting that hsa_circ_0070963 may be a candidate anti-fibrotic target." (PMID 32003753, 2020). "Finally, we demonstrated that hsa_circ_0070963 inhibited CCl4-induced liver fibrosis in mice by modulating the miR-223-3p/LEMD3 axis." (PMID 32003753, 2020). "Furthermore, evidence for hsa_circ_0070963 functionality in liver fibrosis was also shown to involve regulation of the miR-223-3p-LEMD3 axis." (PMID 32003753, 2020). "Here, we show that hsa_circ_0070963 inhibits liver fibrosis via regulation of miR-223-3p and LEMD3." (PMID 32003753, 2020).
chondrocalcinosis (1 paper, 2021). An acute episode of pain, swelling, and redness, sometimes associated with fever. "Other potential genes that were studied in patients with DISH and chondrocalcinosis (DISH/CC) include R-spondin 4 (RSPO4), LEM domain-containing 3 (LEMD3), and protein phosphatase 2 regulatory subunit beta delta 2 (PPPR2RD)." (PMID 33923907, 2021).
Ovarian cyst (1 paper, 2010). The presence of one or more cysts of the ovary. "Interestingly, patients affected with both LEMD3 and EXT1 mutations presented spectrum of additional non-skeletal pathologies, which included: (IV:15) TOF and ovarian cysts, (IV:17) sinus cysts, and (III:13) diabetes melitus type 2 and vitiligo." (PMID 20618940, 2010).
bone disorder (2 papers, 2023 to 2025). "TMEM53 has been linked to a bone disorder in humans that is very similar to a disease caused by mutations in the INM protein MAN1 (LEMD3), consistent with an important function at the NE." (PMID 37433644, 2023). "The CTDNEP1-FLAG precipitates were also highly enriched in MAN1 (also known as LEMD3), an understudied INM resident protein with links to TGFβ/BMP signaling and mutated in bone disorders characterized by excessive TGFβ/BMP signaling." (PMID 40216785, 2025).
LEMD3 also shares sentences with these, for which no sentence is quoted: tumor (2 papers); autoimmune disease (1); autosomal dominant disease (1); Branchio-oculo-facial syndrome (1); laminopathies (1); localized scleroderma (1); multiple exostosis syndrome (1); oculodentodigital dysplasia (1); osteopetrosis (1); scleroderma (1); SHORT syndrome (1); tuberculosis (1); vitiligo (1).